IGF1 (insulin like growth factor 1)
Diseases named in the same sentence as IGF1 in open-access papers (continued):
Sharing a sentence is not in itself a finding about the gene and the disease.
Hirsutism (3 papers, 2021 to 2022). Abnormally increased hair growth referring to a male pattern of body hair (androgenic hair). "Excess GH levels, and therefore excess GHR stimulation and excess IGF-1 levels are associated with hypertrichosis and hirsutism." (PMID 34948002, 2021).
hyperplastic polyp (3 papers, 2016 to 2025). A polyp found mainly in the stomach and colon. "Hyperplastic polyps and carcinoma have been associated with higher levels of serum GH, although higher IGF-1 levels are also associated with increased risks." (PMID 28025627, 2016). "In one study, serum GH levels were correlated directly with finding polyps during a colonoscopy, particularly adenomatous polyps, and serum IGF-1 levels also correlated directly with the likelihood of finding adenomatous and hyperplastic polyps." (PMID 40088375, 2025).
Hypokalemia (3 papers, 2023 to 2024). An abnormally decreased potassium concentration in the blood. "In addition, some patients may present with hypokalemia, which occurs secondary to the insulin-like intracellular effects, and in rare cases, patients may exhibit acromegaloid features in the absence of elevated GH or IGF-1 due to the stimulation of IGF-II stimulation of IGF receptors." (PMID 39219958, 2024).
hypoxic-ischemic encephalopathy (3 papers, 2015 to 2025). "Alteration of IGF-1 level is thought to be also one of the features of the white matter disorders developing in a result of the experienced perinatal asphyxia." (PMID 32691304, 2020). "With aim of addressing the question about the potential impact of neonatal hypoxia-ischemia on the IGF-1 availability in the affected brains, the animal in vivo model of perinatal asphyxia was used." (PMID 32691304, 2020). "The recent clinical studies confirmed that the IGF-1 level in serum is significantly decreased in newborns with hypoxic-ischemic encephalopathy." (PMID 32691304, 2020). "Taken together, these findings suggest that IGF-1 may represent a new neuroprotectant for newborns with hypoxic-ischemic encephalopathy." (PMID 41256775, 2025). "Pharmacological modulation of IGF-1 secretion by neural cells could be reasonable solution in studies aimed at searching for therapies alleviating the consequences of perinatal asphyxia." (PMID 32691304, 2020).
ischemia reperfusion injury (3 papers, 2015 to 2026). Adverse functional, metabolic, or structural changes in ischemic tissues resulting from the restoration of blood flow to the tissue (reperfusion), including swelling; hemorrhage; necrosis; and damage from free radicals. "Studies have explored that short-term exogenous IGF1 treatment was sufficient to preserve cardiac function in animal models of ischemia-reperfusion injury." (PMID 41560804, 2026). "There has been researches that showed that IGF-1 played a vital role in the inhibition of apoptosis, and IGF-1 could significantly reduce the apoptosis number of myocardial cells after ischemia-reperfusion injury." (PMID 26844226, 2015).
Lipedema (3 papers, 2022 to 2025). Disorder of adipose tissue characterized by symmetric and bilateral enlargement of the lower extremities due to abnormal deposition of subcutaneous fat often in obese women. "Insulin-like growth factor 1 (IGF-1) levels were significantly higher in undifferentiated ADSCs and lower in mature differentiated adipocytes of lipedema compared to control cells." (PMID 36551837, 2022). "However, in an in vitro study on fat stem cells, it was found that IGF-1 expression was significantly increased during the proliferation process in stem cell cultures obtained from patients with lipedema compared to the control group." (PMID 40419722, 2025). "Thus, the higher IGF-1 levels noted in the early stages of adipogenesis, followed by the later decreased expression, might contribute to the pathologic phenotype of hyperproliferative adipocytes in lipedema." (PMID 36551837, 2022). "There are no studies in the literature specifically examining the GH/IGF-1 pathway in patients with lipedema." (PMID 40419722, 2025).
lymphoid leukemia (3 papers, 2021 to 2024). A malignant lymphocytic neoplasm of B-cell or T-cell lineage involving primarily the bone marrow and the peripheral blood. "Mitogenic activity of IGF-1 was also found in both myeloid and lymphoid leukemia cell lines." (PMID 35884921, 2022).
mammary adenocarcinoma (3 papers, 2008 to 2022). "Our engineered, PAPP-A resistant IGFBP4 (dBP4) retained IGF1 binding capacity and inhibited IGF1 activation of Akt as well as IGF1-induced migration and invasion by 4T1.2 mammary adenocarcinoma cells." (PMID 30348128, 2018). "Auraptene arrests MCF-7 mammary adenocarcinoma cells in the S phase through alteration of some of the transcription genes involved in cell cycle progression, including the down-regulation of cyclin D1 protein expression level and the suppression of insulin-like growth factor-1 (IGF-1)." (PMID 35267408, 2022). "We previously demonstrated that wild type IGFBP4 inhibited IGF1-induced proliferation of microvascular endothelial cells in vitro and that IGF1 increased VEGF production by 4T1.2 mammary adenocarcinoma cells, suggesting that dBP4 would have anti-angiogenic effects." (PMID 30348128, 2018).
McCune-Albright syndrome (3 papers, 2011 to 2021). McCune-Albright syndrome (MAS) is classically defined by the clinical triad of fibrous dysplasia of bone (FD), cafe-au-lait skin spots, and precocious puberty (PP). "One of these patients required no further therapy, while the other (who had McCune-Albright syndrome) was switched to pegvisomant, which successfully reduced IGF-1 levels to -1 SD, consistent with the literature." (PMID 22024364, 2011).
men (3 papers, 2017 to 2025). "Suspecting multiple endocrine neoplasia syndrome, relevant investigations revealed normal serum prolactin, normal serum insulin-like growth factor 1 (IGF-1) (age and pubertal status matched), normal sella (on CEMRI), and non-elevated 24-hours urinary metanephrine and nor-metanephrine." (PMID 32129057, 2020).
metastasis (3 papers, 2018 to 2021). The spread or migration of cancer cells from one part of the body (where they first appeared) to another. "Association of the expression of MDM2, IGF1, STAT1, and RAC1 and clinical characteristics such as age, gender, Campanicci grade, pathological fracture, and lung metastasis was also analyzed using the Kendall's tau-b test." (PMID 29651441, 2018).
metastatic prostate carcinoma (3 papers, 2013 to 2018). A carcinoma that arises from the prostate gland and has spread to other anatomic sites. "Patients with metastatic prostate cancer had lower serum IGF‐1 than those with localized disease (128.0 vs 143.8 ng/mL, P = 0.023)." (PMID 29992746, 2018). "Our previous study demonstrated that the insulin-like growth factor-1 (IGF-1) and the cytochrome P450 aromatase (CYP19) polymorphisms were significantly associated with the cancer -specific survival of metastatic prostate cancer." (PMID 23530598, 2013). "The genomic variations in the IGF-1 combined with conventional clinicopathological prognostic markers, along with conventional clinical markers, appeared to be useful for predicting the outcome of metastatic prostate cancer." (PMID 23530598, 2013). "Several mechanisms of IGF-1 affecting the prognosis of metastatic prostate cancer are envisioned." (PMID 23530598, 2013).
morbid obesity (3 papers, 2014 to 2020). An excess of body weight, normally defined as an individual with a body mass index greater than 35 or a body weight greater than one hundred percent of ideal body weight. "The main result of the present study is that IGF-1 values are decreased in patients with morbid obesity, and that weight loss after bariatric surgery drives a progressive increase in GH and IGF-1." (PMID 32806629, 2020). "We hypothesized that the GH–IGF-1 axis is altered during morbid obesity due to hormonal and inflammatory adjustments, and that weight loss induced by bariatric surgery increases GH and IGF-1 values." (PMID 32806629, 2020). "IGF-1 levels are higher in morbid obesity and these cases are often tall." (PMID 25541898, 2014).
myeloid neoplasm (3 papers, 2021 to 2025). Proliferation of myeloid cells originating from a primitive stem cell. "Reduced IGF1 levels have also been shown to accelerate HSPC aging and increase susceptibility to myeloid malignancies." (PMID 41339619, 2025).
nodular goiter (3 papers, 2017 to 2021). Goiter characterized by discrete tissue mass(es) that may or may not produce thyroid hormones. "Based on these results, the authors suggested a possible role of IGF-1 in the pathogenesis of nodular goiter." (PMID 29081797, 2017). "Our study found that intranodular IGF-1 and IGFBP-3 levels were significantly higher in subjects with multinodular thyroid gland compared to subjects with solitary nodules which may indicate the role of IGF-1 and IGFBP-3 in nodular goiter pathogenesis." (PMID 29081797, 2017).
parathyroid adenomas (3 papers, 2017 to 2023). "CaSR, MEN1, CCND1/PRAD, CDKI, angiogenic factors like VEGF, FGF, TGFβ, and IGF1, and apoptotic factors are important genes in parathyroid adenomas pathogenesis that have been established by several studies." (PMID 37223014, 2023). "VEGF, FGF, TGFβ, and IGF1 factors were found to be correlated with parathyroid adenoma." (PMID 37223014, 2023). "Recent research suggests that growth factors, for instance insulin-like growth factor-1 (IGF-1), FGF-23 and vascular endothelial growth factor (VEGF) not only modulate insulin sensitivity but also play a role in the development of parathyroid adenomas and hyperplasia." (PMID 29294178, 2018).
periventricular leukomalacia (3 papers, 2022 to 2025). Periventricular leukomalacia (PVL) is a brain injury disorder characterized by the death of the white matter of the brain due to softening of the brain tissue. "We have also shown that the combination of Tf and IGF-1 supports myelination in a mouse model of periventricular leukomalacia and the demyelinated adult brain." (PMID 35743828, 2022).
pituitary apoplexy (3 papers, 2014 to 2026). A rare, potentially life-threatening disorder caused by acute ischemic infarction or hemorrhage in the pituitary gland. "Even though there was a clear chronological relation between the head trauma and the decrease in GH and IGF-1 levels, there are causes other than head trauma that might trigger pituitary apoplexy." (PMID 25182385, 2014). "Magnetic resonance imaging (MRI) revealed a large sellar/suprasellar lesion, and hormonal profile confirmed elevated insulin-like growth factor 1 (IGF-1) with low levels of prolactin, luteinizing hormone (LH), follicle-stimulating hormone (FSH), and testosterone, consistent with pituitary apoplexy." (PMID 41625684, 2026).
Primary biliary cirrhosis (3 papers, 2013 to 2022). "Primary biliary cirrhosis (PBC) has been mainly linked to a low bone-turnover state resulting from decreased production of growth factors such as IGF-1, elevated levels of lithocholic acid (known to prevent osteoblast formation), and vitamin K deficiency." (PMID 34205986, 2021).
Primary Hypertension (3 papers, 2021 to 2024). "Recently, we presented converging evidence that linked vascular dysfunction that arises as a result of age-related decrease in growth hormone and insulin-like growth factor-1 (IGF-1) on microvascular rarefaction (MVR) and loss of blood vessels, leading to primary hypertension." (PMID 33962396, 2021).
prion disease (3 papers, 2016 to 2023). A transmissible disease that is caused by a protein that is able to induce abnormal folding of normal cellular proteins, leading to characteristic spongiform brain changes, which are associated with neuronal loss without an inflammatory response. "IGF1 has been linked to neuronal survival in cell culture models of prion disease and is a factor that has been shown to be neuroprotective in other models of neurodegenerative disease, such as ALS18,19." (PMID 30705335, 2019). "A similar trend is observed for IGF1 expression, which is upregulated in prion disease and appears to be microglia associated." (PMID 26541819, 2016).
psychological distress (3 papers, 2022 to 2025). "Therefore, the stress-induced immune response modified by IGF-1 may explain the sex difference in the association between psychological distress and EBV serological reactivation." (PMID 36279393, 2022). "It has also been reported that community-dwelling older adults who participate in social activities have faster gait speeds, lower levels of psychological distress, higher cognitive function, lower inflammation, and higher IGF-1 values." (PMID 38030967, 2023). "Reduced neurotrophic support (IGF-1), heightened apoptotic and oxidative signaling (CASP-9 and nNOS), and deficient anti-inflammatory control (IL-10) jointly foster neuronal instability and emotional dysregulation." (PMID 41150816, 2025).
pycnodysostosis (3 papers, 2020 to 2023). Pycnodysostosis is a genetic lysosomal disease characterized by short stature, increased density of the bones (osteosclerosis/osteopetrosis), and brittle bones. "Change in anthropometric measures of five patients with pycnodysostosis during follow-up, rhGH response and IGF-1 measurements in the first, second, and third case, and BMD z-score on admission." (PMID 37809147, 2023). "Despite disproportionate short stature being mainly attributed to skeletal features, former studies have reported lower circulating IGF-1 levels in pycnodysostosis when compared to other etiologies of short stature." (PMID 37809147, 2023). "Short stature is a cardinal phenotype of pycnodysostosis, and some studies have reported reduced growth in pycnodysostosis patients possibly due to lower levels of IGF-1." (PMID 34680947, 2021). "GH treatment, based on an IGF-1-based dosing regimen, when offered to three children with pycnodysostosis and 16 children of idiopathic short stature, resulted in near-normal stature and body proportion." (PMID 32248673, 2020).
RASopathy (3 papers, 2018 to 2022). Developmental syndromes caused by germline mutations (or in rare cases by somatic mosaicism) in genes that alter the Ras subfamily and mitogen-activated protein kinases that control signal transduction. "Of note, IGF1 was low in patients 3 and 5 in spite of normal GH concentrations in response to provocation, and this may reflect neurosecretory dysfunction of GH secretion, as has also previously been documented in RASopathy patients." (PMID 33795686, 2021).
retinal (3 papers, 2012 to 2021). "Similar to the effects of IGF1, NMDA-induced retinal damage causes the transient accumulation, distal migration and reactivity of the NIRG cells." (PMID 22973454, 2012).
retinal detachment (3 papers, 2014 to 2024). An eye emergency condition which may lead to blindness if left untreated. "The elevation of IGF-1 level during retinal detachment is a homeostatic response to diverting energy utilization from the external glucose supply to the internal supply through lipid oxidation." (PMID 38397833, 2024). "The second phase is induced by hypoxia, which causes elevated levels of growth factors, such as vascular endothelial growth factor (VEGF) and insulin-like growth factor-1 (IGF-1) with resultant vaso-proliferation, neovascularization, and potential retinal detachment with subsequent vision loss." (PMID 25561234, 2014).
sarcoidosis (3 papers, 2013 to 2024). Sarcoidosis is a multisystemic disorder of unknown cause characterized by the formation of immune granulomas in involved organs. "TNFα, PAI-1, and IGF-1 levels in EBC were closely positively correlated with BALF samples from sarcoidosis patients." (PMID 26464848, 2013). "An increase of IGF-1 and IGF-1R expression in alveolar macrophages (AM) and ATII cells is observed in IPF and sarcoidosis." (PMID 30018981, 2018). "Nonetheless, various cytokines which are able to support a fibrotic response have been found at disease sites in patients with sarcoidosis (e.g., transforming growth factor-β (TGF-β), MMP, and insulin growth factor-1 (IGF-1))." (PMID 26464848, 2013).
Seizure (3 papers, 2025). A seizure is an intermittent abnormality of nervous system physiology characterized by a transient occurrence of signs and/or symptoms due to abnormal excessive or synchronous neuronal activity in the brain. "The plasma elevation of proinflammatory cytokines (IL-1; IL-6; TNF-alpha; INF-gamma), which is traditionally associated with epileptic seizures, is countered by the elevation of anti-inflammatory mechanisms (IL-10; Fractalkine; GCSF) and the decrease in plasma concentration of IGF-1." (PMID 40076950, 2025). "The modulation of IGF-1 may influence both the frequency and severity of epileptic seizures, thus providing a rationale for developing therapeutic strategies." (PMID 40371354, 2025).
seminoma (3 papers, 2015 to 2018). A radiosensitive malignant germ cell tumor found in the testis (especially undescended), and extragonadal sites (anterior mediastinum and pineal gland). "From them, EC-, pluripotency- and reprogramming-associated genes REX1 (ZFP42), DND1, JARID2 and PRDM14 were hypomethylated and upregulated, while seminoma-related genes PRDM1, PROM1 and IGF1 became hypermethylated and were downregulated." (PMID 26226633, 2015).
sexual dysfunction (3 papers, 2015 to 2024). Disturbances in sexual desire and the psychophysiologic changes that characterize the sexual response cycle and cause marked distress and interpersonal difficulty. "The link between GH and IGF1 excess and sexual dysfunction in women has been less extensively elucidated as compared to men." (PMID 36165745, 2022). "A strong link between GH and IGF1 excess and sexual dysfunction in men has been documented." (PMID 36165745, 2022).
Silver-Russell syndrome (3 papers, 2020 to 2024). Silver-Russell syndrome is characterized by growth retardation with antenatal onset, characteristic facies and limb asymmetry. "Also, in children with Silver-Russell syndrome (caused by various (epi)genetic disorders, including IGF2 and other gene mutations), a PAPPA2 mutation, Bloom syndrome and IGF1 mutations, IGF-I can be increased or in the upper half of the reference range." (PMID 31842524, 2020).
skin aging (3 papers, 2015 to 2024). The gradual irreversible changes in structure of skin that occur as a result of the passage of time.. "GH and IGF-1 have been associated with skin aging in previous studies, but results were controversial." (PMID 37916150, 2023). "In conclusion, the data presented in this study suggests that IGF-1, glucose, and cortisol associate with perceived age independent of each other and may thus lead to skin aging via distinct biological mechanisms." (PMID 25874752, 2015). "Transcription factor JunB‐induced inhibition of IGF‐1 promotor activation decreases the levels of IGF‐1 and its downstream PI3K/AKT pathway effectors, resulting in disruption of the metabolic and structural niches of skin stem cells, consequently leading to exacerbation of skin aging." (PMID 38040661, 2024).
Stillbirth (3 papers, 2022 to 2024). Death of the fetus in utero after at least 22 weeks of gestation. "It increased serum IGF-1 levels in primiparous and multiparous sows, leading to improved birth results, such as increased total births, higher survival rates, and reduced stillbirths." (PMID 38672296, 2024).
synovial sarcoma (3 papers, 2019 to 2021). "However, Igf1, which is downstream of the Cyclin D1 pathway, was upregulated both in tumors and eMCs expressing SS18-SSX1, which might be important for drug resistance in synovial sarcoma treatment." (PMID 32019274, 2020).